MTOR (mechanistic target of rapamycin kinase)
Diseases named in the same sentence as MTOR in open-access papers (continued):
Sharing a sentence is not in itself a finding about the gene and the disease.
medulloblastoma (continued). "Interestingly, the miR-183/96/182 cluster has been demonstrated to enhance PI3K/AKT/mTOR signaling and promote cell migration in medulloblastoma, with the majority of this effect attributed to miR-182." (PMID 24627810, 2014). "Overall, these findings supported the concept that enhanced PI3K/Akt/mTOR signaling in medulloblastoma CSCs is responsible for radioresistence of these cells, and that Akt inhibition could increase radiosensitivity." (PMID 24281174, 2010). "Thus, inhibiting enhanced protein synthesis by targeting the MYC indirectly and mTOR pathways together may present a highly appropriate strategy for treating MYC-driven medulloblastoma and other MYC-addicted cancers." (PMID 39779613, 2025). "Likewise, MYC and mTOR signaling activation has been demonstrated to synergize together in cancer biology, directing tumor deterioration and drug resistance in several malignancies, including medulloblastoma." (PMID 39779613, 2025). "Furthermore, our high frequency MB mouse model carrying activation of both the Shh and the PI3K/AKT/mTOR pathways could be a tool suitable to represent the subset of patients with this type of medulloblastoma." (PMID 34395258, 2021). "So, in order to simultaneously target MYC, mTOR/PI3K, and cyclin pathways, a combination of ribociclib was tested with BET-bromodomain JQ1 and paxalisib on group 3 medulloblastoma cell lines." (PMID 40862786, 2025). "PI3K/mTOR inhibitors have shown synergistic effects and advantages with BET and CDK inhibitors to treat group 3 and SHH medulloblastoma in preclinical tumor models." (PMID 39779613, 2025). "Not only that, but also the crosstalk between SHH and other oncogenic pathways that are commonly overactivated in medulloblastoma, such as PI3K/mTOR and RAS/REF/MEK, can play a significant role in evading SMO inhibition." (PMID 37568705, 2023). "A miR-592-mediated activation of mTOR (mammalian target of rapamycin), ERK1/ERK2 signaling, and neuronal differentiation impart group 4 medulloblastoma characteristics." (PMID 36467881, 2022). "For instance, PI3K/MTOR inhibition can delay therapeutic resistance against SMO inhibitors in mouse models of cancer, including BKM120 cotreatment in HH-driven medulloblastoma or cotreatment with the MTOR inhibitor RAD-001 in esophageal adenocarcinoma." (PMID 34268113, 2021). "The second-generation mTOR, AZD8055 and sapanisertib, suppressed medulloblastoma cell growth; however, limited studies have investigated possible resistance pathways." (PMID 35008889, 2021). "In summary, these findings highlight a key role for PI3K/mTOR signalling in GLI1 regulation in HH-driven cancers and suggest that combined PI3Kα/mTOR inhibition may be particularly interesting for the development of effective treatment strategies in high-risk medulloblastomas." (PMID 31492956, 2019). "Remarkably, pharmacologic mTOR inhibition was found to reduce tumour growth and increase survival in a SMO inhibitor resistant medulloblastoma transgenic mouse model." (PMID 31492956, 2019). "For example in a mouse model of medulloblastoma, addition of PI3K inhibitor BKM120 or PI3K/mTOR inhibitor BEZ235 to the initial treatment with SMO inhibitor LDE225 markedly delayed the occurrence of resistance." (PMID 25749378, 2015). "Further, targeting this enhanced protein synthesis pathway with combined inhibition of MYC transcription and mTOR translation by small-molecule inhibitors, demonstrates preclinical synergistic anti-tumor potential against MYC-driven medulloblastoma in vitro and in vivo." (PMID 39779613, 2025). "MTOR signaling itself is another key regulator of protein synthesis which is frequently deregulated in various cancers, including MYC-addicted cancers and medulloblastoma." (PMID 39779613, 2025). "Moreover, EPHB2 mediated malignant progression of medulloblastoma by regulating ERK, P38 and mTOR pathway." (PMID 36032135, 2022).
medulloblastoma (continued). "In addition, SMO inhibitor-resistant mouse medulloblastoma are still sensitive to PI3K inhibition and combination therapy with the GLI inhibitor GANT61 and PI3K/MTOR inhibitor PI103 synergistically inhibited tumors in a HH-driven rhabdomyosarcoma mouse model." (PMID 34268113, 2021). "Thus, we sought to investigate the effects of simultaneous inhibition of PI3Kα and mTOR in DAOY and D556 medulloblastoma cells." (PMID 31492956, 2019). "Another important clue to the role played by PI3K/Akt/mTOR signaling in conferring CSC resistance to therapeutic treatments, comes from a study which has documented that in mice medulloblastoma CD133+/nestin+ CSCs (which are located in perivascular niches), radiation activated Akt/mTOR signaling." (PMID 24281174, 2010). "No clinical trials have been found to treat medulloblastoma using third-generation mTOR inhibitors." (PMID 35008889, 2021). "Indeed, our previous studies demonstrate that the key components of protein synthesis machinery, including mTOR signaling and MYC targets, are overexpressed and activated in MYC-amplified medulloblastoma, confirming MYC-dependent addiction of enhanced protein synthesis in medulloblastoma." (PMID 39779613, 2025).
rhabdomyosarcoma (42 papers, 2011 to 2025). A rare aggressive malignant mesenchymal neoplasm arising from skeletal muscle. "Based on PPTP/C results, a randomized phase 2 trial was conducted for patients with relapsed rhabdomyosarcoma comparing the mTOR inhibitor temsirolimus to bevacizumab, with each agent being given with vinorelbine plus cyclophosphamide." (PMID 39510293, 2024). "Curcumin was previously demonstrated to induce a G1/G0 cell cycle arrest and cell death through inhibition of mTOR, in a pair of rhabdomyosarcoma cell lines, with a reported IC50 of 2.5 μM after 6 days treatment." (PMID 36771452, 2023). "We initially validated our system using the dual PI3K/mTOR inhibitor BEZ235 was tested on the rhabdomyosarcoma cell culture U484842." (PMID 34857796, 2021). "mTOR activation has been observed in rhabdomyosarcoma (RMS); however, mTOR complex (mTORC) 1 inhibition has had limited success thus far." (PMID 32709151, 2020). "GLI has been found amplified and expressed in several tumor types, including rhabdomyosarcoma, and treatment of a human rhabdomyosarcoma cell line with the mTOR inhibitor rapamycin inhibits its growth." (PMID 33081032, 2020). "On the other hand, induction of apoptosis by the treatment of GANT61 and PI103, a PI3K/mTOR inhibitor, shows synergistic effect but the signals are mediated through different effector molecules in rhabdomyosarcoma." (PMID 27349387, 2016). "Previous studies have shown promise by targeting the PI3K/AKT/mTOR pathway in rhabdomyosarcoma." (PMID 36771452, 2023). "In addition, another pan-deacetylase inhibitor panobinostat showed effectiveness in inducing Hodgkin’s lymphoma cell death, while a pan-mTOR inhibitor aided in rhabdomyosarcoma cell apoptosis." (PMID 26247207, 2015). "Thus, the combination of an anti-IGF-IR antibody with mTOR inhibitors was shown to block the Akt-signaling pathway in rhabdomyosarcoma, breast, and prostate carcinomas, resulting in an additive increase in cell growth-inhibition." (PMID 23548153, 2013). "The study in rhabdomyosarcoma demonstrated miR-206 was the upstream of ACTL6A, and miR-206 was identified to regulate EMT via PI3k/Akt/mTOR signaling, which was also the classical EMT related signaling." (PMID 30348114, 2018). "Recent studies in rhabdomyosarcoma have concluded that combined inhibition of MEK and mTOR is synergic because of anti-counteractive interaction: each drug blocks reciprocal activation of the other pathway." (PMID 25955301, 2015). "Recent studies of rhabdomyosarcoma have concluded that combined inhibition of MEK and mTOR is synergic because of anti-counteractive interaction: each drug blocks reciprocal activation of the other pathway." (PMID 25955301, 2015). "Another study has reported that concurrent blockade of the PI3K/AKT/mTOR (with mTOR inhibitor AZD8055) and RAS/MEK/ERK (with MEK inhibitor AZD6244) pathways synergistically inhibits rhabdomyosarcoma cell growth." (PMID 25170609, 2014). "Activated Akt can activate or deactivate its multiple substrates, including mammalian target of rapamycin (mTOR), bcl-2 family member BAD, transcription factor forkhead homolog 1 in rhabdomyosarcoma (FKHR), Mdm2 protein, glycogen synthase kinase 3 (GSK3) and many others, via its kinase activity." (PMID 22107784, 2011). "However, this does not exclude a role for mTOR-dependent regulation of Chk2 in the DNA damage response as a recent report shows that in response to DNA damage, mTORC1 through FANCD2 is required for ATM-Chk2 activation in rhabdomyosarcoma cells." (PMID 25460505, 2015).
chondrosarcoma (41 papers, 2011 to 2025). A malignant cartilaginous matrix-producing mesenchymal neoplasm arising from the bone and soft tissue. "An example involves miR-100, a tumor suppressor miRNA that plays a significant role in chondrosarcoma progression by targeting and inhibiting the mammalian target of the rapamycin (mTOR) signaling pathway, which is involved in tumor growth and metastasis." (PMID 38542153, 2024). "These inhibitors have shown effectiveness in preclinical chondrosarcoma models, underscoring the mTOR pathway’s role in potentially improving treatment outcomes for this challenging malignancy." (PMID 39590345, 2024). "Targeting the mTOR pathway with inhibitors like rapamycin and everolimus further reduces tumor metabolism and progression, underscoring their potential to enhance chondrosarcoma treatment outcomes." (PMID 39590345, 2024). "Target therapies with potential activity in chondrosarcoma include antiangiogenic agents, mTOR inhibitors, hedgehog inhibitors, histone deacetylase inhibitors, immunotherapy, and, more recently, IDH inhibitors." (PMID 37752419, 2023). "The mTOR inhibitor rapamycin reduced oxidative and glycolytic metabolism and dose-dependently decreased cell viability in chondrosarcoma cell lines." (PMID 35163019, 2022). "Our study demonstrates that visfatin enhances PDGF-C production and facilitates EPC angiogenesis in human chondrosarcoma cells by inhibiting miR-1264 production in the PI3K/Akt/mTOR signaling pathway." (PMID 36359873, 2022). "In another study, the mTOR inhibitor everolimus suppressed the expressions of Glut1 and HIF1α, cell proliferation, and prevented tumor progression in a rat orthotopic chondrosarcoma model." (PMID 35163019, 2022). "Human chondrosarcoma-derived cell lines demonstrated phosphorylation of receptor tyrosine kinases (RTKs), particularly AKT, MEK and S6 kinase suggesting clinical relevance of the PI3K/ATK/mTOR pathway in chondrosarcoma." (PMID 34938658, 2021). "Dual PI3K/mTOR inhibition was studied in a chondrosarcoma xenograft model and demonstrated significant suppression of growth utilizing BEZ235 and GCD-041 with rapamycin." (PMID 34938658, 2021). "The mTOR inhibitors sapanisertib and rapamycin have also been studied in chondrosarcoma cell lines and they induce decreased oxidative and glycolytic metabolism, independent of IDH status." (PMID 34938658, 2021). "Clinical studies of mTOR pathway inhibition in chondrosarcoma hold promise given the encouraging pre-clinical data." (PMID 34938658, 2021). "The PI3K/Akt signaling pathway regulates downstream mTOR activity and together they control the metastatic potential of chondrosarcoma." (PMID 34815382, 2021). "Another ongoing phase I/II study is investigating combined nivolumab and the mTOR inhibitor ABI-009 in patients with chondrosarcoma and other advanced malignancies (ClinicalTrials.gov (accessed on 2 March 2021) Identifier: NCT03190174)." (PMID 34067530, 2021). "Inhibition of mTOR in chondrosarcoma cell lines and animal models has led to anti-tumor responses via reduction of glycolysis, oxidative metabolism, cellular proliferation, and Glut1 and HIF-1α expression." (PMID 34067530, 2021). "Phosphorylation of S6, a downstream marker for mTOR activity, has been shown to have increased activity in up to 69% of conventional and 44% of dedifferentiated chondrosarcoma." (PMID 32707689, 2020). "A previously performed metabolic compound screen revealed an mTOR inhibitor, sapanisertib, as an effective anti-proliferative agent for chondrosarcoma." (PMID 33425984, 2020). "In line with this, it has been reported that treatment of rat chondrosarcoma cells with mTOR inhibitor, everolimus blocked cell proliferation and tumor progression." (PMID 31139331, 2019).
chondrosarcoma (continued). "Most important, we found that EGFR is activated through an autocrine loop and showed that inhibition of EGFR profoundly reduced the activation of both ERK1/2 and AKT/mTOR signaling and decreased cell proliferation and migration of chondrosarcoma cells." (PMID 31139331, 2019). "This suggests that CCN6 increases MMP-9 expression and induces cell metastasis in human chondrosarcoma cells via the PI3K/Akt/mTOR/NF-κB signaling pathway." (PMID 30237403, 2018). "Metformin and phenformin decreased mTOR activity in chondrosarcoma cells, and metformin decreased LC3B-II levels, which is counteracted by chloroquine." (PMID 29576625, 2018). "CCN6 appears to depend upon activation of the PI3K, Akt, and mTOR signaling pathways to induce NF-κB activation in human chondrosarcoma cells." (PMID 30237403, 2018). "In another study, protein hormone adiponectin promoted VEGF-A expression in human chondrosarcoma cell lines via PI3k, Akt, mTOR, and hypoxia-inducible factor-1a signaling cascades." (PMID 29546033, 2018). "In chondrosarcoma, reduced expression of miR-100 was associated with resistance to CDDP with activation of the Akt-mTOR pathway." (PMID 28978183, 2017). "Upregulated expression of miR-100 sensitized chondrosarcoma cells to CDDP by inhibiting the Akt/mTOR pathway." (PMID 28978183, 2017). "Based on these results, it appears that the adiponectin acts through the PI3K, Akt and mTOR pathway to enhance VEGF-A expression in human chondrosarcoma cells." (PMID 26468982, 2015). "Western blot combined with immunohistological analyses showed a strong expression of phospho-Akt, phospho-mTOR, and phospho-p70S6K in the orthotopic chondrosarcoma model, indicating that the mTOR signaling pathway is activated in chondrosarcoma." (PMID 22761648, 2012). "In the chondrosarcoma model the activity of the mTOR pathway in response to the different treatments was monitored by following activation levels of 4EBP1, S6K as potential surrogate markers of tumor response." (PMID 22761648, 2012). "In this work, we demonstrate the therapeutic role of mTOR inhibition in chondrosarcoma in localized and advanced phase." (PMID 22761648, 2012). "MTOR inhibitor everolimus blocks cell proliferation, Glut1 expression and HIF1a expression, and prevents in vivo chondrosarcoma tumor progression in both macroscopic and in adjuvant phase post R1 resection." (PMID 22761648, 2012). "The aim of the present study was to determine the antitumor effects of doxorubicin and everolimus, an mTOR inhibitor on chondrosarcoma progression." (PMID 22761648, 2012). "A clinical trial evaluating mTOr inhibitor as neo-adjuvant and adjuvant therapy in chondrosarcoma patients is being constructed." (PMID 22761648, 2012). "This revealed that the mTOR pathway was inhibited by RAD-001 in chondrosarcoma cells contrary to 15-47 cells, in particular eIF4G and p70 S6 kinase whose phosphorylation level was decreased." (PMID 21437224, 2011). "MiR-199 has been found to reverse cisplatin resistance in human ovarian cancer cells by inhibiting mTOR, a pathway that could also be a target of miR-199a in chondrosarcoma." (PMID 38542153, 2024). "Recently, Palubeckaite and colleagues have generated an alginate-based 3D cell culture model of chondrosarcoma to evaluate the treatment of chemotherapeutic drugs and target therapeutic agents including Sapanisertib (mTOR inhibitor) and AGI-519 (inhibitor of mutant IDH1)." (PMID 36622753, 2023). "Thus, visfatin appears to increase PDGF-C synthesis in chondrosarcoma cells through PI3K/Akt/mTOR signaling." (PMID 36359873, 2022). "Similarly, the mTOR pathway was studied in a preclinical rat chondrosarcoma model by utilizing the mTOR inhibitor everolimus which blocked cell proliferation as well as GLUT1 and HIF1a expression in vivo." (PMID 34938658, 2021). "Treatment of chondrosarcoma cell lines with NGF upregulated mTOR phosphorylation." (PMID 34815382, 2021).